NDRG1 (N-myc downstream regulated 1)
Diseases named in the same sentence as NDRG1 in open-access papers (continued):
Sharing a sentence is not in itself a finding about the gene and the disease.
breast carcinoma (continued). "The most recent and comprehensive review by Zhao and Richardson suggests that the role of NDRG1 may be independent of breast cancer subtypes." (PMID 37858101, 2023). "Therefore, there exists a negative correlation between NDRG1 protein expression and TNBC, indicating that increased NDRG1 protein expression is associated with the aggressive features of breast cancer." (PMID 37858101, 2023). "This modulation may be mediated by the upregulation of the kinase gene SGK1, which activates the AP-1/NDRG1 axis in both progesterone receptor (PR)-positive and -negative breast cancer cells." (PMID 37395734, 2023). "Our study suggests that increased expression of NDRG1 by preoperative progesterone exposure may help to mitigate the negative effects of surgical stress on breast cancer cells." (PMID 37395734, 2023). "However, we found that NDRG1 is critical in promoting tumorigenesis and brain metastasis in mouse models of inflammatory breast cancer (IBC), a rare but highly aggressive form of breast cancer." (PMID 33321961, 2020). "However, no increase in NDRG1 expression was evident in ErbB2 breast cancer cells cultured in the presence of MEDICA." (PMID 32695336, 2020). "In addition, we followed up 190 breast cancer patients for over 10 years and conducted a survival analysis for the positivity of expression (EpCAM, FADD, and αB-crystallin) or the level of expression (NDRG1) in the primary tumor sites." (PMID 31443698, 2019). "Our meta-analysis of the relationship between NDRG1 mRNA expression and prognosis in large populations of patients with breast cancer is definitive: overexpression of NDRG1 mRNA is a significant negative prognostic factor in breast cancer." (PMID 29898756, 2018). "Kaplan–Meier analysis showed that the overall survival rates were significantly lower in breast cancer patients with than without amplification of one of these genes (log rank test; NDRG1, P = 0.0554; UBR5, P = 0.0122; MYC, P = 0.0094; EXT1, P = 0.0103; NBN, P = 0.0030; and COX6C, P = 0.0073)." (PMID 28977883, 2017). "Treatment of breast cancer cell lines ZR‐75‐1 and CAMA‐1 that have low levels of SGK1 with structurally diverse Akt inhibitors (MK‐2206 and AZD5363) for 1 h inhibited phosphorylation of PRAS40 (Thr246, Akt‐specific substrate) as well as NDRG1 (Thr346, Akt and SGK substrate)." (PMID 27481935, 2016). "However, in studies of breast cancer tissues, the methylation status of NDRG1 has not been reported." (PMID 23899187, 2013). "Furthermore, the NDRG1 promoter methylation correlated with the Tumor Node Metastasis (TNM) at stage III/IV, metastasis, lymph invasion, moderate and poor histological grade in the breast cancer patients." (PMID 23899187, 2013). "NDRG1 protein expression and human epidermal growth factor receptor 2 (Her2) status were found to have a negative relationship (P = 0.01, log OR: -0.76, 95% CI: -1.32–(-0.20), I2: 32.42%, 197 breast cancer cases with Her2 positive and 272 breast cancer cases with Her2 negative, 3 studies)." (PMID 37858101, 2023). "However, the expression level of NDRG1 had no prognostic value for breast cancer patients." (PMID 31443698, 2019). "We describe that SGK1 regulates the expression of NDRG1 via regulation of expression of EGR1, a transcription factor from the AP-1 network genes, in breast cancer independent of the PR status of cells." (PMID 30337371, 2018).
prostate carcinoma (83 papers, 2006 to 2025). A carcinoma that arises from epithelial cells of the prostate gland. "A number of studies in prostate cancer have demonstrated that NDRG1 associates with androgen receptors and inhibits a range of critical signalling pathways, including EGFR, HER2, HER3, PI3K, and STAT3." (PMID 36765657, 2023). "Two other studies have revealed a tumor suppressor role for NDRG1 in prostate cancer in association with the role of this protein in modulation of AR activity." (PMID 37249826, 2023). "Spearman correlation analysis revealed that NDRG1 pS330 levels in prostate cancer are associated with AR pS213 (r = 0.3664, p = 0.01) and PIM1 protein levels (r = 0.5038, p = 0.00003)." (PMID 33398037, 2021). "Using a three‐dimensional invasion assay and an in vivo metastasis assay for human prostate xenografts, we demonstrate that NDRG1‐deficient prostate cancer cells exhibit a collective invasion phenotype and are highly invasive." (PMID 28371345, 2017). "Independent studies have shown that low NDRG1 levels are associated with worse prognosis for patients with breast, glioma, colorectal, esophageal squamous cell carcinoma, and prostate cancer." (PMID 27894074, 2017). "To investigate the effect of NDRG1 loss in prostate cancer cells, we generated stable knockdown of NDRG1 using Mission Lentiviral System (Sigma) as described in our previous reports." (PMID 28371345, 2017). "Elucidating pathways that drive survival and invasiveness of NDRG1‐deficient prostate cancer cells can help in designing therapeutics to target metastatic prostate cancer cells." (PMID 28371345, 2017). "However, the loss of NDRG1 activates the NF-κB pathway, leading to the induction of epithelial-mesenchymal transition in prostate cancer." (PMID 38235128, 2023). "Moreover, high NDRG1 expression is associated with worse overall survival in treatment-naïve prostate cancer patients." (PMID 36765657, 2023). "NDRG1 is a transcription factor that is implicated in growth arrest, cell differentiation, and response to hypoxia, and it is regarded as an anti-metastatic molecule in prostate carcinoma." (PMID 30135355, 2018). "Targeting EMMPRIN/MMPs axis in NDRG1‐deficient prostate tumors could be an attractive therapeutic option to decrease prostate cancer metastasis." (PMID 28371345, 2017). "Intriguingly, certain phenotypes associated with metastasis such as matrix adhesion, cell spreading, and motility, which otherwise have been shown to increase after loss of metastasis suppressors, were severely hampered in prostate cancer cells that were deficient in NDRG1." (PMID 28371345, 2017). "This indicates that loss of NDRG1 results in increase in prostate cancer invasion." (PMID 28371345, 2017). "To study the behavior of cells deficient in NDRG1, we first examined the expression of NDRG1 in a panel of prostate cancer cell lines (DU145, LNCaP, and PC3 cells), normal immortalized prostate cells (RWPE and 957E/hTERT cells), and nontumorigenic HEK293 cells." (PMID 28371345, 2017). "In addition to previously known androgen-regulated biological processes associated with prostate cancer progression, such as NDRG1 that helped to validate our proteomic study, our list of androgen-regulated proteins was enriched for aminoacyl tRNA synthetases." (PMID 19763266, 2009). "However, the molecular mechanisms that lead NDRG1‐deficient prostate cancer cells to increased invasiveness remain largely unknown." (PMID 28371345, 2017). "While these latter studies were reported using hepatocellular carcinoma cells, NDRG1 regulatory activity differs in pancreatic cancer cells, prostate cancer cells, and colon cancer cells." (PMID 40378957, 2025). "PTEN-silencing resulted in increased levels of phosphorylated NDRG1 at Thr346 in DU-145 prostate cancer cells, where the anti-oncogenic effect of NDRG1 is observed." (PMID 40378957, 2025). "This and other studies support the role of NDRG1 as a potential tumour suppressor in human colon and prostate cancer." (PMID 40332138, 2025).
prostate carcinoma (continued). "NDRG1 has also been demonstrated to inhibit androgen signaling in prostate cancer cells to suppress cellular proliferation and migration." (PMID 40378957, 2025). "These in vivo findings are supported by prior studies in prostate cancer cells, where NDRG1 regulates cell-cell adhesion via Rab4-mediated recycling of E-cadherin." (PMID 40462946, 2025). "Studies on prostate cancer cells have shown an interaction between NDRG1 and Rab4a, as well as their localisation in recycling/sorting endosomes." (PMID 40332138, 2025). "In patients with prostate cancer, it has been demonstrated that NDRG1 mRNA and protein expression levels are reduced in patients with prostate cancer, indicating a poor prognosis and higher tumor grade." (PMID 40378957, 2025). "NDRG1 expression has been shown to inhibit the invasion and metastasis of prostate cancer, pancreatic cancer, and colon cancer cells." (PMID 40151835, 2025). "NDRG1 facilitates the progression of bladder cancer 53, liver cancer 54, ovarian cancer 55, prostate cancer 56, and esophageal squamous cell carcinoma 57 via EMT." (PMID 39744686, 2025). "Both the present investigation examining PC cells and our previous studies using prostate cancer and colon cancer cells also demonstrated that NDRG1 expression inhibited β-catenin phosphorylation at Ser552 promoting its transcriptional activity." (PMID 38815861, 2024). "Proteomic analysis in human prostate cancer and benign prostatic hyperplasia samples have revealed association between over-expression of YWHAZ and NDRG1 and poor prognosis based on Gleason scores." (PMID 37249826, 2023). "In contrast to previous investigations in colorectal and prostate cancer cells 19, Vimentin was inhibited after NDRG1 silencing in MDA-MB-231 and MDA-MB-436 cells treated with TGFβ1, which was not seen in SUM159 and BT549." (PMID 36594086, 2023). "A chemical genetic screening method for identification of substrates for the oncogenic serine/threonine kinase PIM1 has led to identification of NDRG1 as an important substrate for this kinase in prostate cancer cells." (PMID 37249826, 2023). "Another study in prostate cancer has shown that N-cadherin induces expression of c-Jun and inhibits expression of NDRG1 to increase invasive properties and migratory potential of prostate cancer cells via affecting epithelial to mesenchymal transition (EMT)." (PMID 37249826, 2023). "Second, the impact of MLL5α on activation of AR/NDRG1 signaling has been found to result in the suppression of prostate cancer progression." (PMID 37249826, 2023). "Knocking down NDRG1 in prostate cancer cells increased Cdc42 activity, a protein involved in cell cycle regulation as well as in resistance to anoikis, a process often preceding metastasis." (PMID 36497221, 2022). "One of the molecular pathways involved in regulating prostate cancer metastasis is NDRG1 gene that its down-regulation results in increased migration." (PMID 35773731, 2022). "For example, in prostate cancer cells NDRG1 was found to colocalize with markers for recycling endosomes, as well as for late endosomes, and was shown to be involved in the recycling of E-cadherin." (PMID 36497221, 2022). "Mechanistically, LINC00844 mediates AR binding to chromatin and its expression is vital for promoting NDRG1 gene expression in suppressing prostate cancer migration and invasion." (PMID 35773731, 2022). "NDRG1 is an androgen-regulated gene, making it a central protein of interest in Prostate cancer (PrCa) and a target of study for many years." (PMID 36497221, 2022). "The translation of the ERG gene gives rise to different fusion gene products, such as TMPSSR2-ERG and NDRG1-ERG in prostate cancer, EWS-ERG in Ewing’s sarcoma, and FUS-ERG in acute myeloid leukemia." (PMID 36009466, 2022).
prostate carcinoma (continued). "The tumour suppressor PTEN (phosphatase and tensin homologue) has been shown to upregulate NDRG1 expression in breast and prostate cancers." (PMID 36497221, 2022). "We next examined the subcellular distribution of NDRG1 pS330 and total NDRG1 in prostate cancer cells." (PMID 33398037, 2021). "We next probed a panel of prostate cancer cell lines for NDRG1 pS330, total NDRG1, and PIM1 by western blot." (PMID 33398037, 2021). "VCaP cells, a prostate cancer cell line with AR amplification, displayed the highest level of total NDRG1 and NDRG1 pS330, consistent with our findings that NDRG1 expression and phosphorylation are androgen-regulated." (PMID 33398037, 2021). "Similar stimulative effect of NDRG1 was also observed in prostate cancer with regard to the EMT process." (PMID 34965023, 2021). "Immunohistochemical analysis of prostate cancer tissue microarrays showed a significant increase in NDRG1 pS330 in malignant compared to benign tissues." (PMID 33398037, 2021). "NDRG1 can interact with the Wnt receptor LRP6 in prostate cancer cells, inhibiting Wnt signalling cascade." (PMID 33520115, 2021). "Together, these results demonstrate that NDRG1 pS330 is correlated with high-grade prostate cancers (high Gleason score), and that NDRG1 pS330 is present in multiple prostate cancer cell lines." (PMID 33398037, 2021). "In light of these findings, and given the previously demonstrated ability of PIM1 to promote cell migration and invasion, we investigated the effect of NDRG1 phosphorylation on the migration and invasion of prostate cancer cells." (PMID 33398037, 2021). "This suggests that PIM1-mediated phosphorylation of NDRG1 inhibits its ability to exert metastasis-suppressive functions in prostate cancer." (PMID 33398037, 2021). "Another study reported that LINC00844 exerted its antitumour activity by regulating the expression of NDRG1 in prostate cancer." (PMID 32025371, 2020). "On the other hand, E6AP targets the metastasis suppressor NDRG1 (N-Myc Downstream Regulated 1) that was reported in mesenchymal phenotypes of prostate cancer." (PMID 32882786, 2020). "NDRG1 expression is very low in many tumor types and inhibits metastatic progression in patients with prostate cancer." (PMID 32550915, 2020). "A recent report showed that LINC00844 inhibited tumour metastasis by regulating the expression of NDRG1 in prostate cancer." (PMID 32025371, 2020). "We showed that treatment of prostate cancer cells with pharmacological agents upregulated NDRG1 expression suppressed E6AP-induced cell migration." (PMID 31739170, 2019). "NDRG1 has been widely deemed a tumor suppressor gene in numerous types of cancers, including prostate cancer." (PMID 31581708, 2019). "MIEN1 also can affect NDRG1 gene expression in prostate carcinoma cells via the Akt signal pathways." (PMID 31581708, 2019). "Interleukin-6 (IL-6), a pluripotency cytokine, is involved in the malignant progression of prostate cancer, while N-myc downstream regulated 1 (NDRG1) is a tumor suppressor gene in numerous cancer cells, including prostate." (PMID 31581708, 2019). "The reporter assays showed that transient-cotransfected MIEN1 expression vector decreased the reporter activity of NDRG1 reporter vector in prostate carcinoma PC-3 and LNCaP cells." (PMID 31581708, 2019). "Studies of prostate cancer cells and healthy kidney tissue have identified truncated isoforms of NDRG1, with molecular masses varying from 35 to 40 kDa." (PMID 31029158, 2019). "Our result is in line with our studies showing that CAPE treatments downregulated cyclin E expression in human prostate carcinoma PC-3 and overexpression of NDRG1 in human glioma U87 MG cells blocked cyclin E expression." (PMID 29738439, 2018). "The expression of GPNMB in prostate cancer cell lines and animal models results in the activation of N-myc downstream-regulated gene 1 (Ndrg1) in-vitro and in-vivo." (PMID 30400781, 2018).
prostate carcinoma (continued). "NDRG1 has been reported to correlate with metastasis in prostate cancer, pancreatic cancer, and colorectal cancer." (PMID 30185791, 2018). "Of the handful of metastasis suppressors in prostate cancer, NDRG1 has been a relatively recent addition." (PMID 28371345, 2017). "The well‐characterized Dunning AT6.1 spontaneous prostate cancer metastasis model aided in identification of NDRG1 as a metastasis suppressor gene." (PMID 28371345, 2017). "Experimental and clinical evidence suggests that N‐myc downregulated gene 1 (NDRG1) functions as a suppressor of prostate cancer metastasis." (PMID 28371345, 2017). "Expression of NDRG1 inversely correlates with Gleason grading and overall prostate cancer patient survival." (PMID 28371345, 2017). "In clinical studies, NDRG1 was inversely correlated with breast and prostate cancer metastasis, while being positively correlated with patient survival." (PMID 26431493, 2015). "Taken together, we suggest that the anticancer effect of VPA on prostate cancer cells is, in part, mediated through upregulation of NDRG1." (PMID 26692161, 2015). "Taken together, these data support a role for NDRG1 in inhibiting c-Abl activation in both the prostate cancer cell lines, DU145 and PC3MM, and the colon cancer cell line, HT29." (PMID 25860930, 2015). "In prostate cancer cells, NDRG1 overexpression has been shown to maintain membrane E-cadherin and inhibit TGF-β-induced EMT." (PMID 26692161, 2015). "The expression of NDRG1 has also been demonstrated to have a significant inverse correlation with the Gleason grading and overall survival rate of prostate cancer patients, as well as the depth of tumor invasion in pancreatic adenocarcinoma patients." (PMID 26125440, 2015). "In another study, the small molecule L-mimosine promoted HIF-1α expression, as well as NDRG1 expression, in prostate cancer cells, thereby inhibiting prostate cancer proliferation." (PMID 25232961, 2014). "NDRG1 has also been shown to influence Wnt signaling and there is a prima facie case for the involvement of NDRG1 in the regulation of Wnt signaling in prostate cancer cell lines." (PMID 24386364, 2013). "The presence of NDRG1 using these antibodies was compared in the human prostate cancer cell lines, DU145, PC3 and LNCaP, against primary cultures of normal human PrEC." (PMID 23634903, 2013). "As NDRG1 has been identified as a metastasis suppressor gene in colon and prostate cancer, it is possible that p21 is a molecular player in its antimetastatic activity." (PMID 24260043, 2013). "In HCC, the expression and function of NDRG1 is controversial, but in prostate cancer, the gene expression in patients with lymph node or bone metastasis is significantly reduced compared with that in patients with localized prostate cancer." (PMID 24260043, 2013). "This is highlighted by the fact that overexpression of NDRG1 in a prostate cancer cell line results in inhibition of metastasis in vitro and in vivo." (PMID 23634903, 2013). "Western-blot analysis of PrECs and the three prostate cancer cell lines was then performed using two NDRG1 primary antibodies targeted to either the C-terminal epitope of NDRG1 (amino acids 384–392) or the N-terminal epitope of NDRG1 (amino acids 19–48)." (PMID 23634903, 2013). "In prostate cancer, however, it has been shown that NDRG1 overexpression maintains membrane E-cadherin and β-catenin and inhibits TGF-β-induced EMT, thus inhibiting cell migration and invasion." (PMID 24260043, 2013).